OSBPL6 (oxysterol binding protein like 6)
Description:
Regulates cellular transport and efflux of cholesterol. Plays a role in phosphatidylinositol-4-phophate (PI4P) turnover at the neuronal membrane. Localizes at the neurons plasma membrane-endoplasmic reticulum contact sites, and exchanges phosphatidylserine (1,2-diacyl-sn-glycero-3-phospho-L-serine, PS) from the endoplasmic reticulum for phosphatidylinositol-4-phosphate (1,2-diacyl-sn-glycero-3-phospho-(1D-myo-inositol 4-phosphate), PI(4)P) from the plasma membrane (By similarity). Binds via its PH domain PI4P, phosphatidylinositol-4,5-diphosphate, phosphatidylinositol-3,4,5-triphosphate, and phosphatidic acid (By similarity). Weakly binds 25-hydroxycholesterol.
Synonyms: ORP6
Tractability: Antibody: UniProt places it where antibodies can reach, with high confidence; its Gene Ontology location is reachable by antibodies, with high confidence; the Human Protein Atlas places it where antibodies can reach. PROTAC: ubiquitination databases record sites on it; its protein half-life has been measured.
Gene: Protein-coding gene on chromosome 2 (178,193,711 to 178,402,893, forward strand). Ensembl gene ENSG00000079156.
Subcellular location: Cytoplasm, cytosol; Endoplasmic reticulum membrane; Nucleus envelope; Cell membrane; Endosome membrane
Subcellular location (Human Protein Atlas): Plasma membrane
Pathways (Reactome):
Metabolism: Synthesis of bile acids and bile salts
Gene Ontology:
Molecular function: protein binding; cholesterol binding; phosphatidylserine-phosphatidylinositol-4-phosphate exchange activity; sterol transfer activity; lipid binding
Biological process: regulation of cholesterol transport; bile acid biosynthetic process; intermembrane phospholipid transfer; sterol transport
Cellular component: cytosol; early endosome membrane; endoplasmic reticulum membrane; endosome membrane; nuclear membrane; perinuclear endoplasmic reticulum; plasma membrane; endoplasmic reticulum-plasma membrane contact site; nuclear envelope
Genetic constraint (gnomAD): Loss-of-function variants: 38 observed, 104.75 expected, observed/expected ratio (o/e) 0.36, 90% interval 0.28 to 0.47. The upper end of that interval is the gene's LOEUF score, 0.47, which puts it in group 2 of 6, group 1 being the genes least tolerant of losing a copy. Missense variants: 859 observed, 1,030.7 expected, observed/expected ratio (o/e) 0.83, 90% interval 0.79 to 0.88. Synonymous variants: 340 observed, 355.53 expected, observed/expected ratio (o/e) 0.96, 90% interval 0.87 to 1.05.
Homologues: Orthologues: chimpanzee OSBPL6 (99% identical), macaque OSBPL6 (99% identical), pig OSBPL6 (98% identical), dog OSBPL6 (98% identical), guinea pig OSBPL6 (98% identical), rabbit OSBPL6 (98% identical), mouse Osbpl6 (98% identical), rat Osbpl6 (97% identical), tropical clawed frog osbpl6 (82% identical), zebrafish osbpl6 (75% identical), Drosophila melanogaster CG3860 (18% identical), Caenorhabditis elegans obr-2 (14% identical). Paralogues in human: OSBPL3 (56% identical), OSBPL7 (47% identical), OSBP2 (25% identical), OSBPL1A (25% identical), OSBP (24% identical), OSBPL2 (19% identical), OSBPL5 (18% identical), OSBPL8 (18% identical), OSBPL10 (17% identical), OSBPL9 (16% identical), OSBPL11 (15% identical).
Diseases named in the same sentence as OSBPL6 in open-access papers:
OSBPL6 is named in the same sentence as 7 diseases in open-access papers, as found by Europe PMC text mining. Sharing a sentence is not in itself a finding about the gene and the disease. The quoted sentences say what the papers report.
Alzheimer disease (1 paper, 2025). A progressive, neurodegenerative disease characterized by loss of function and death of nerve cells in several areas of the brain leading to loss of cognitive function such as memory and language. "Utilizing a multivariate phenotype that integrates disease status and age at onset and identified a significant association between genetic variation in OSBPL6 (rs1347297) and the risk of Alzheimer’s disease (AD)." (PMID 41049486, 2025).
atherosclerosis (1 paper, 2021). A disease characterized by the build-up of fatty material and calcium deposition in the arterial wall resulting in partial or complete occlusion of the arterial lumen. "While it remains to be determined whether miR‐33‐mediated silencing of OSBPL6 affects cholesterol efflux to HDL‐C levels in vivo, OSBPL6 mRNA levels positively correlate with ApoA1 and HDL‐C levels in humans and OSBPL6 levels are decreased in the carotid arteries of patients with atherosclerosis." (PMID 33938628, 2021).
dyslipidemia (1 paper, 2025). "Alterations in plasma lipid profiles and local brain lipid dysmetabolism, evident in Osbpl6−/− mice, may underlie the observed neurological changes, particularly considering the established connection between dyslipidemia, blood brain barrier integrity, and neurodegenerative processes." (PMID 40716750, 2025).
liver cancer (1 paper, 2023). An epithelial or non-epithelial malignant neoplasm that arises from the liver. "Taken together, these results imply that OSBPL2, OSBPL3, and OSBPL6 were potentially involved in liver cancer progression." (PMID 36918840, 2023). "The mRNA of OSBPL2, OSBPL3, and OSBPL8 were highly expressed while OSBPL6 was lowly expressed in liver cancer samples compared with normal samples." (PMID 36918840, 2023).
multiple sclerosis (1 paper, 2020). A progressive autoimmune disorder affecting the central nervous system resulting in demyelination. "The oxysterol-binding protein-like 6 (OSBPL6) gene encodes the oxysterol-binding protein-like 6 receptor, which associated with multiple sclerosis (P = 4.64 × 10−4) in the United Kingdom (UK) population." (PMID 32258092, 2020). "It is not a surprise that ITP shares some immune mechanisms with multiple sclerosis; thus, OSBPL6 may participate in the pathogenesis of ITP in terms of immune regulation." (PMID 32258092, 2020).
tumor (1 paper, 2023). "The results demonstrated that the protein expressions of OSBPL2 and OSBPL3 were elevated while OSBPL5, OSBPL6, OSBPL9, OSBPL10, and OSBPL11 were lowly expressed in tumor samples." (PMID 36918840, 2023). "As to the protein expression, OSBPL2 and OSBPL3 were significantly elevated and OSBPL5, OSBPL6, OSBPL9, OSBPL10, OSBPL11 were downregulated in tumor samples." (PMID 36918840, 2023).
OSBPL6 also shares sentences with these, for which no sentence is quoted: coronary artery disease (1 paper).